SLC25A14 (solute carrier family 25 member 14)
Description:
Transports inorganic anions (sulfate, sulfite, thiosulfate and phosphate) and, to a lesser extent, a variety of dicarboxylates (e.g. malonate, malate and citramalate) and, even more so, aspartate and glutamate and tricarboxylates. May catalyze the export of sulfite and thiosulfate (the hydrogen sulfide degradation products) from the mitochondria, thereby modulating the level of the hydrogen sulfide (Probable). Also can mediate a very low unidirectional transport of anions including sulfate, phosphate, (S)-malate, citrate, L-aspartate and L-glutamate. Maintains oxidative balance (through uncoupling activities) and ATP production (by modifying mitochondrial membrane potential). Is able to transport protons across lipid membranes. Also exhibits transmembrane chloride transport activity to a lesser extent. May modify mitochondrial respiratory efficiency and mitochondrial oxidant production (By similarity).
Synonyms: BMCP1; UCP5
Tractability: Antibody: its Gene Ontology location is reachable by antibodies, with high confidence; UniProt predicts a signal peptide or a membrane-spanning region. PROTAC: its protein half-life has been measured.
Gene: Protein-coding gene on chromosome X (130,339,888 to 130,373,361, forward strand). Ensembl gene ENSG00000102078.
Subcellular location: Mitochondrion inner membrane
Subcellular location (Human Protein Atlas): Mitochondria
Pathways (Reactome):
Metabolism: The fatty acid cycling model
Gene Ontology:
Molecular function: chloride transmembrane transporter activity; protein homodimerization activity; proton transmembrane transporter activity; solute:inorganic anion antiporter activity
Biological process: inorganic anion transport; regulation of cellular response to oxidative stress; aerobic respiration; chloride transmembrane transport; proton transmembrane transport; transmembrane transport
Cellular component: mitochondrion; mitochondrial inner membrane; plasma membrane
Homologues: Orthologues: macaque SLC25A14 (99% identical), guinea pig SLC25A14 (98% identical), pig SLC25A14 (97% identical), dog SLC25A14 (91% identical), rabbit SLC25A14 (91% identical), chimpanzee SLC25A14 (90% identical), rat Slc25a14 (90% identical), mouse Slc25a14 (87% identical). Paralogues in human: SLC25A30 (72% identical), SLC25A27 (36% identical), UCP2 (34% identical), UCP3 (34% identical), UCP1 (31% identical), SLC25A12 (27% identical), SLC25A13 (26% identical), SLC25A35 (26% identical), SLC25A11 (24% identical), SLC25A22 (24% identical), SLC25A29 (24% identical), SLC25A4 (24% identical), and 37 more.
Diseases named in the same sentence as SLC25A14 in open-access papers:
SLC25A14 is named in the same sentence as 19 diseases in open-access papers, as found by Europe PMC text mining. Sharing a sentence is not in itself a finding about the gene and the disease. The quoted sentences say what the papers report.
autism (3 papers, 2012 to 2021). Persistent deficits in social interaction and communication and interaction as well as a markedly restricted repertoire of activity and interest as well as repetitive patterns of behavior. "The RBMX2 gene is also located adjacent to the Solute Carrier Family 25 Member 14 (SLC25A14) gene, which has been shown to have altered expression in autism patients." (PMID 34914762, 2021). "The expression of DNAJC19, DNM1L, LRPPRC, SLC25A12, SLC25A14, SLC25A24 and TOMM20 were reduced in at least two of the brain regions of autism patients." (PMID 23116158, 2012). "The expression of DNAJC19, DNM1L, LRPPRC, SLC25A12, SLC25A14, SLC25A24 and TOMM20 were consistently reduced in at least two of the brain regions of autism patients compared to controls." (PMID 23116158, 2012). "We observed a reduced expression of SLC25A12 and SLC25A14 in the ACG and MC of autism patients." (PMID 23116158, 2012).
Alzheimer disease (1 paper, 2025). A progressive, neurodegenerative disease characterized by loss of function and death of nerve cells in several areas of the brain leading to loss of cognitive function such as memory and language. "These are two brain-specific uncoupling proteins (SCL25A27 and SLC25A14) and three genes linked to Alzheimer Disease (PSEN1, PSEN2, and BACE1)." (PMID 40901366, 2025).
cervical squamous cell carcinoma (1 paper, 2022). A squamous cell carcinoma arising from the cervical epithelium. "Some genes of SLC25 were associated with poor prognosis of patients in cervical squamous cell carcinoma and endocervical adenocarcinoma, including SLC25A4, SLC25A5, SLC25A8, SLC25A14, SLC25A12, SLC25A23, and SLC25A41." (PMID 36254139, 2022).
colon cancer (1 paper, 2024). "Noteworthy research by Kuai reveals that SLC25A14, through a feedback mechanism for mitochondrial dysfunction, exerts inhibitory control over the escalation of H2O2 products in colon cancer." (PMID 38801430, 2024).
ovarian carcinoma (1 paper, 2022). A malignant neoplasm originating from the surface ovarian epithelium. "In addition, ovarian cancer patients with higher mRNA levels of the UCP5 (SLC25A14) were predicted to have improved OS and PPS (p < 0.05)." (PMID 35090503, 2022). "Meanwhile, ovarian cancer patients at Stage 1, 2, 4 and Grade 2, 3 were predicted to have longer OS when they have higher mRNA levels of the UCP5(SLC25A14)." (PMID 35090503, 2022).
uterine corpus endometrial carcinoma (1 paper, 2022). A endometrial carcinoma (disease) that involves the body of uterus. "Almost all SLC25s had high mutation frequency in uterine corpus endometrial carcinoma, including SLC25A12, SLC25A13, SLC25A14, SLC25A23, SLC25A24, and SLC25A25." (PMID 36254139, 2022).
cancer (2 papers, 2024 to 2025). A tumor composed of atypical neoplastic, often pleomorphic cells that invade other tissues. "While UCP1, UCP3, SLC25A27, and SLC25A14 were frequently downregulated in most cancers, UCP2 showed consistent upregulation, indicating divergent functional roles in oncogenesis." (PMID 41403699, 2025). "These consistent expression patterns suggest that UCP2 may function as an oncogene in diverse cancer contexts, while UCP1, UCP3, SLC25A27, and SLC25A14 are potentially involved in tumor-suppressive mechanisms." (PMID 41403699, 2025).
tumor (2 papers, 2022 to 2025). "UCP1, UCP3, SLC25A27, and SLC25A14 showed significantly lower expression in most tumor tissues." (PMID 41403699, 2025).
SLC25A14 also shares sentences with these, for which no sentence is quoted: atherosclerosis (2 papers); autism spectrum disorder (1); diabetes (1); endocervical adenocarcinoma (1); Hypertension (1); leukemia (1); neurodegenerative disease (1); Parkinson disease (1); prostate carcinoma (1); psychiatric disorder (1); Stroke (1).